INS (insulin)
Diseases named in the same sentence as INS in open-access papers (continued):
Sharing a sentence is not in itself a finding about the gene and the disease.
diabetes (continued). "Reports have confirmed the beneficial role of gallic acid in the management of diabetes and diabetic complications such as diabetic nephropathy and cardiomyopathy, neuropathy due to its potent antioxidant, anti-inflamamtory TGF-β inhibitory activity and by increasing insulin sensitivity." (PMID 34149415, 2021). "Another factor influencing the Cu/Zn ratio is hormone signaling, particularly the decline of insulin, GH, and IGF-1, which are all stimulators of albumin synthesis, and this decline is common in elderly or pathological conditions such as diabetes or pre-diabetes." (PMID 34066564, 2021). "However, the disadvantage is that blood insulin levels are not routinely checked for patients without diabetes in the primary clinical setting." (PMID 34735502, 2021). "Because my glucose level dropped and I could not stand on my feet, I didn’t inject my insulin many times out of this fear” (A 60-year-old female patient with diabetes)." (PMID 33461565, 2021). "Consistently, fasting insulin level in BMS309403-treated mice was also higher compared with that in vehicle-treated mice, suggesting that pharmacological inhibition of FABP4 from an early age is sufficient to ameliorate β cell destruction and diabetes in NOD mice." (PMID 33690220, 2021). "As HBOT improved insulin sensitivity and glycaemic control through increased tissue oxygenation, we hypothesized that the improved tissue oxygenation provided by ELO water would lower blood glucose in a setting of diabetes." (PMID 34260650, 2021). "However, this ability of beta cells to secrete insulin in these extremes of hyperglycemia is what distinguishes hyperosmolar hyperglycemic nonketoic syndrome from diabetic ketoacidosis." (PMID 34205432, 2021). "Diabetes is a chronic noncommunicable diseases (CNCDs) characterized by chronic hyperglycemia resulting from defects in secretion and action of the pancreatic hormone insulin." (PMID 34429169, 2021). "However, due to the lack of information about diabetic medication and diabetes duration, which affect insulin signaling in the brain, these findings should be interpreted with caution." (PMID 34959979, 2021). "Insulin-treated patients were more likely to be female, of non-white race, to have a longer duration of diabetes and a history of heart failure, to have a prior history of myocardial infarction or coronary revascularization, and to receive high-intensity statin treatment." (PMID 34158057, 2021). "Of these 68 colorectal programs using a preoperative CCD, 98.5% administered a beverage to patients without diabetes, 79.7% administered a beverage to patients with diabetes not taking insulin, and 60.9% administered a beverage to patients with diabetes taking insulin (p < 0.05)." (PMID 34044894, 2021). "Regarding its role in the onset of diabetes, a novel hypothesis is emerging: LCN2 may be upregulated during the earliest stage of diabetes to promote β-cell function and insulin sensitivity but this protective mechanism is eventually overwhelmed when diabetes settles." (PMID 34638803, 2021). "It is known that type 2 diabetes mellitus (non-insulin dependent diabetes) is a metabolic disease characterized by chronic hyperglycemia, which develops as a result of a violation of the interaction of insulin with tissue cells." (PMID 34639150, 2021). "Given the potency of somatostatin in inhibiting glucagon and insulin secretion, it is not surprising that defects in δ-cell function and aberrant regulation of paracrine interactions play a fundamental role in the development of diabetes." (PMID 33494193, 2021). "Only 27.7 and 39.4% disagreed and strongly disagreed that people who do not need to take insulin to treat their diabetes have a mild disease, and people whose diabetes is treated by just a diet do not have to worry about getting many long-term complications, respectively." (PMID 33579243, 2021).
diabetes (continued). "In addition, many African countries currently struggle with early diagnosis of diabetes due to a lack of facilities and personnel with patients also struggling to routinely monitor their insulin levels." (PMID 34249838, 2021). "Furthermore, in individuals without diabetes, the addition of fructose to diets in isocaloric exchange for other macronutrients does not affect insulin sensitivity." (PMID 33673073, 2021). "Similarly, Hnf1a mouse models with heterozygous KO present without developing diabetes, whereas a homozygous KO impairs β-cell function by reducing the insulin secretion." (PMID 34079523, 2021). "Eighty percent of the participants in this study took Metformin as a prescribed diabetes medication which may explain the lack of significant changes in insulin sensitivity and glycemic control." (PMID 34930480, 2021). "Of note, in none of these trials a negative effect on diabetes control, insulin requirements or β-cell function could be observed." (PMID 33868284, 2021). "However, after adjusting the diabetes status and family history of diabetes, the first pattern showed no significant relation with serum insulin, IR, and insulin sensitivity." (PMID 33499915, 2021). "Increased ROS production occurs in mitochondria in diabetes and malfunction is considered as one of the key elements at subcellular level responsible for diabetic complications such as production of advanced-glycation end-products (AGE), insulin secretion and resistance, and oxidative stress." (PMID 34064568, 2021). "Systemic administration of members of IGF axis was reported to improve glycemic control in T2DM patients as well as insulin sensitivity and pancreatic β-cell functions making IGF proteins promising candidates as therapeutic modalities for obesity, insulin resistance and diabetes." (PMID 34940355, 2021). "For instance, in studies of transgenic globular adiponectin ob/ob mice partial amelioration of insulin resistance and diabetes, but not of obesity were found implying that sustainably high levels of globular adiponectin have insulin-sensitizing effect, which is independent of WAT." (PMID 35018766, 2021). "Similarly, in the present study diabetes did not appear to be secondary to insulin resistance since insulin sensitivity was similar in all groups." (PMID 34234216, 2021). "In addition, since the insulin analog BiAsp30 was not used for improving diabetes control, our study allows for a better understanding of the pharmacokinetics of the premixed insulin preparations." (PMID 34063071, 2021). "Furthermore, persons receiving insulin (both type I diabetes and type II diabetes) have similar recommendations regarding their SMB (such as the self-measurement of their blood glucose [SMBG] and keeping a diabetes-diary)." (PMID 33740024, 2021). "Diabetes is a metabolic disease characterized by a chronic increase in blood glucose levels; it occurs when the pancreas does not produce enough insulin due to the autoimmune destruction of ß cells (type 1 diabetes) or when the body cells become resistant to insulin (type 2 diabetes)." (PMID 34594393, 2021). "However, those with advanced CP without diabetes exhibited reduced beta cell mass, and the expression of pancreatic and duodenal homeobox gene as well as insulin gene decreased in these patients." (PMID 34566890, 2021). "While IGF-1 has insulin-agonistic actions and has been used for treatment of severe insulin resistance, IGF-1 reduction with the GH antagonist pegvisomant improves glycemic control in acromegalic patients with diabetes or impaired glucose tolerance despite elevated GH." (PMID 33995272, 2021). "It is worth discussing that comparison of cluster characteristics in patients with longer duration of diabetes demonstrated that we for sure could not tell which of the two insulin resistant obese clusters in long-term would match the original SIRD and MOD." (PMID 34276762, 2021).
diabetes (continued). "True innovation is lacking with regard to insulin and the delivery of diabetes care." (PMID 33483763, 2021). "Considering that postprandial levels of oxyntomodulin were found to be markedly lower in NODAP compared with T2DM and healthy controls (independent of insulin secretion), it is possible that leptin is an important factor in differentiating the pathogenesis of the two diabetes states." (PMID 34684558, 2021). "However, due to the contemporary in-lab synthesis of insulin, which was considered the greatest development in the therapy of Diabetes Mellitus (DM), the drug did not get much consideration." (PMID 35008275, 2021). "Consistent with previous studies, our study confirmed that weight gain may be the side effect of long-term insulin monotherapy in T1DM, which is the main reason that intensive insulin therapy fails to improve the microvascular and macrovascular complications of diabetes." (PMID 33651228, 2021). "In addition, in a longitudinal 9-year study, lower baseline insulin clearance and decline in insulin clearance measured as the C-peptide to insulin ratio during an OGTT were related to the incidence of prediabetes and diabetes." (PMID 33498493, 2021). "In our series of patients with Covid-19, a substantial number of patients with and without diabetes had admission hyperglycemia and those who were critically ill may have had compromised insulin secretion and lowered sensitivity to insulin." (PMID 33466617, 2021). "Data from patients prescribed hypoglycemic agents from December 2009 to March 2015 were extracted from diabetes specialists’ registries, resulting in a sample size of 4860 patients who had received initial monotherapy with either insulin (n=293) or noninsulin (n=4567)." (PMID 33502325, 2021). "The vicarious insulin secretion not compete with insulin resistance results in diabetes." (PMID 34026064, 2021). "This could be affected by the research methodology and lack of pre-existing diabetes, and low percentage of insulin treated GDM." (PMID 33671089, 2021). "However, despite the increased CGM adoption in insulin-requiring diabetes care as recognized by national and international medical organizations in many countries, successful utilization of CGM data in real-life diabetes care remains relatively low." (PMID 35140679, 2021). "However, clinical outcomes of continuous glucose monitoring in patients with basal insulin treatment has not reduced the rate of hospitalization of patients with diabetes." (PMID 35056977, 2021). "Under prolonged increases in insulin demand, these rare proliferation events may not be sufficient to replace the destroyed beta cell mass, leading to diabetes." (PMID 35155441, 2021). "Treatment for type 1 diabetes mellitus (T1D) has made significant progress over the past 50 years, mainly with the advent of the continuous subcutaneous insulin infusion (CSII) in the 90's, which allows for the patient to obtain more accurate doses of insulin, comfort and safety." (PMID 33320450, 2021). "In situations wherein prescription transmission is not an issue, some people with diabetes may have interrupted or have no access to insulin or consumables." (PMID 32678672, 2021). "In a further prospective observational study, including ICU septic patients with and without diabetes (the first either insulin- and non-insulin treated), the disease progression and mortality for sepsis in diabetic patients was similar regardless of insulin treatment." (PMID 33973089, 2021). "Other characteristics including gender, education, short-acting insulin intake, long-acting insulin intake, dietary supplement intake, daily insulin dose, BMI, weight, WC, diabetes duration, energy intake and physical activity were not significantly different across DPI tertiles (P trend > 0.05)." (PMID 34118879, 2021). "In addition, endocrine pancreas insufficiency was suspected with repeatedly low Insulin levels but without clinical signs of diabetes." (PMID 33259146, 2021).
diabetes (continued). "More importantly, previous studies have demonstrated that MG53 is myokine/cardiokine secreted from striated muscle in response to high glucose and high insulin, which may lead to a remarkable increase in serum MG53 content in rodents and humans with obesity and diabetes." (PMID 34240802, 2021). "Healthy volunteers usually exhibit lower intraindividual variability than patients with type 1 diabetes mellitus, while the presence of type 1 diabetes mellitus could ensure the absence of interference of endogenous insulin." (PMID 33947913, 2021). "However, insulin usage for diabetes treatment was not significantly related to cervical cancer occurrence (χ2 = 2.369, p > 0.05)." (PMID 34332564, 2021). "Calorie restriction (CR) is effective for the improvement of glucose tolerance, but it is not clear whether CR can maintain insulin levels in the late stage of diabetes." (PMID 33916828, 2021). "However, these initial positive views on the prospects of insulin therapy in the 1920s are in harsh contrast to the reality that many people with diabetes face some 100 years later, specifically owing to lack of access to insulin." (PMID 33483763, 2021). "Furthermore, participants in TyG (−) & HOMA-IR (+) group were more probable to get a higher body mass index (BMI), SBP, DBP, FPG, fasting insulin, post load glucose and LDL cholesterol in comparison with TyG (+) & HOMA-IR (−) group and had a higher prevalence of diabetes and hypertension." (PMID 34865646, 2021). "Thus, pancreas-targeted CLU OE causes metabolic deregulation being evident by altered expression of mitochondrial and metabolic genes, along with exaggeration of diabetic phenotypes as manifested by decreased GLU, INS and PYR tolerance in basal conditions or in a model of STZ-induced diabetes." (PMID 33744871, 2021). "Persons with diabetes, fearing stigmatization may be less likely to use or not use therapies that may be visible to “others,” such as taking insulin injections or self-monitoring glucose levels." (PMID 34305751, 2021). "Since the ability to induce insulin secretion is a necessary condition for a compound to exert an anti-diabetes effect, we chose the dose of 10 μM regardless of the possible cytotoxicity that some PCs showed at that concentration (e.g., caffeic acid, vanillic acid, and vanillin)." (PMID 33546278, 2021). "Another possible explanation of our results is that reduction in insulin clearance is a robust compensatory mechanism that does not initially fail, unlike beta-cell compensation, whose failure is considered a key event in the development of diabetes." (PMID 34206745, 2021). "However, the rs9934336 SNP had a nominally significant effect on glucose concentrations and insulin levels in individuals without diabetes in both the main and the control group." (PMID 33974529, 2021). "Furthermore, the increased PA time appears to be effective only among people with mild diabetes, such as those who are not on insulin treatment, or those without established cardiovascular diseases." (PMID 33444338, 2021). "Besides the implication of the insulin/IGF-1 axis, diabetes involve the dysregulation of other hormones, which implicate HIF1 signaling and may promote breast carcinogenesis such as the adiponectin-leptin duo." (PMID 34225729, 2021). "From a clinical perspective, it is well‐known that enhancement of insulin sensitivity, rather than plasma glucose level, has a major role in improving diabetes outcomes, while insulin resistance is a better predictor of future cardiovascular events in nondiabetic individuals." (PMID 33960110, 2021). "In addition, while in this study we identified patients by their diabetes type, no information was collected about usage of insulin, especially among patients with type 2 diabetes." (PMID 35010385, 2021).
diabetes (continued). "In contrast, Type 2 diabetes mellitus (T2DM), responsible for approximately 90% of all diabetes cases, represents a systemic disease characterized by hyperglycemia either in the context of insulin resistance in peripheral tissues or lack of insulin secretion from the pancreas." (PMID 34122330, 2021). "In addition, insulin therapy remarkably increased maternal blood pressure, an effect that persisted after matching age, pre-pregnancy BMI, time and BP at GDM diagnosis, and family history of diabetes and hypertension." (PMID 34579668, 2021). "Moreover, our hypothesis is stressed by the fact that diabetes mellitus type 2 patients had more pronounced VAT as well as SAT areas and the VAT area correlated with higher glucose and insulin concentrations." (PMID 33861804, 2021). "In addition, genes in the mature onset diabetes in young people (hsa04950) pathway (such as HES1, GCK, FOXA3, MAFA, HNF4A, HHEX, and PDX1) were increased in stages II to IV; these genes are related to insulin secretion and the maturation of pancreatic β-cells." (PMID 33897780, 2021). "The results obtained point towards the positive regulation by ladarixin on insulin sensitivity, glucose transporters GLUT1 and GLUT4, cytokine proteome profile and lipid metabolism, thus suggesting ladarixin as a potentially helpful treatment in type 2 diabetes mellitus and obesity." (PMID 34571976, 2021). "Diabetes mellitus is one of the most severe and incurable metabolic disorders, characterized by an increase in blood glucose level due to an absolute or relative lack of insulin and failure of insulin to act on its target tissue." (PMID 33897432, 2021). "Therefore, it is not surprising that important changes in diabetes care, from long-acting insulin to its use in combination with oral drugs, also changed the natural history of the disease in all diabetic patients." (PMID 34063872, 2021). "Although dietary interventions may not eliminate or reverse the need for medication and insulin, this lifestyle modification could reduce the need for these therapies in certain scenarios for patients with diabetes (PWD) (including T1D and T2D)." (PMID 33918343, 2021). "Also, more subjects with prediabetes and diabetes, users of antihyperglycemic, insulin and antihypertensive therapies were in NAFLD than in non-NAFLD group." (PMID 34531465, 2021). "All patients developing DFUs were on insulin, while half of lipodystrophy patients without DFUs were still being treated with oral antidiabetics, another indicator of the presence of more severe diabetes in patients developing foot ulcers." (PMID 34593051, 2021). "Finally, detailed information on anti-diabetes agent use and insulin shots were not available across the whole period of follow-up." (PMID 33919529, 2021). "The effect of added oleic acid in the context of reduced but not absent CD36 could perhaps lead to an insulin-resistant state, and similar to in diabetics, inhibits vessel formation, even in the context of pro-angiogenic signals." (PMID 34888367, 2021). "In Sweden, unlike other EU countries, the Swedish Diabetes Registry is the source of information for the DR screening of patients with type 2 diabetes and type 1 diabetes who are on insulin treatment and for patients with a diagnosis at 30 years of age or younger." (PMID 34204591, 2021). "Diabetes mellitus (DM) is a chronic disease that occurs as the result of the reduction of the insulin hormone in the body or when the body itself is not able to utilise insulin effectively." (PMID 34771213, 2021). "Despite the inclusion criterion of at least 1 U of insulin administration during hospitalization, 31 203 patients (56.8%) had no coded diagnosis of diabetes present on admission; type 2 diabetes was present in 21 660 admissions (39.4%) and type 1 diabetes in 1321 admissions (2.4%)." (PMID 33416883, 2021).